BATF3 (basic leucine zipper ATF-like transcription factor 3)
Diseases named in the same sentence as BATF3 in open-access papers (continued):
Sharing a sentence is not in itself a finding about the gene and the disease.
atherosclerosis (6 papers, 2015 to 2025). A disease characterized by the build-up of fatty material and calcium deposition in the arterial wall resulting in partial or complete occlusion of the arterial lumen. "More recently, a study using Apolipoprotein E-deficient (ApoE-/-) Batf3-/- mice has proposed that Batf3-dependent DCs promote atherosclerosis through induction of Th1 responses in the aorta." (PMID 28771609, 2017). "In this study we aimed to clarify the exact contribution of Batf3-dependent cells in atherosclerosis that comprise both CD8α+ as well as CD103+ APC subsets." (PMID 28771609, 2017). "These divergent results suggest that the role of cDC1s, regulated by BATF3, in atherosclerosis may be influenced by various factors and require further investigation." (PMID 38397127, 2024). "In Apoe−/− mice, Batf3 deletion (Batf3−/−) attenuated CD8α+ DCs, thereby reducing the localization of macrophages to aortic plaques, resulting in the suppression of inflammation and the prevention of atherosclerosis." (PMID 39528464, 2024). "An expression of Batf3 in their precursors may thus potentially also affect the abundance of resident aortic cells or their progeny in atherosclerosis lesions." (PMID 28771609, 2017). "To further clarify whether Batf3 may affect macrophage foam cell formation as a key factor in atherosclerosis, we have generated bone marrow-derived macrophages (BMDMs)." (PMID 28771609, 2017). "Nevertheless, Batf3 deficiency had no impact on atherosclerosis in hyperlipidemic mice." (PMID 40934103, 2025). "Several studies have investigated the role of the basic leucine zipper transcription factor ATF-like 3 (BATF3), which is required for the development of lymphoid tissue cDC1s and peripheral cDC1s, in atherosclerosis, yielding different results." (PMID 38397127, 2024). "We show that full Batf3 deletion did not affect the development of atherosclerosis or alter plaque compositions and was accompanied by only minor changes in the immune response." (PMID 28771609, 2017). "We thus provide evidence that Batf3-dependent antigen-presenting cells do not have a prominent role in atherosclerosis." (PMID 28771609, 2017). "The role of Batf3-dependent APCs in the development of atherosclerosis is not clear." (PMID 28771609, 2017). "Although there is evidence that Batf3 is not required for macrophage differentiation, embryo-derived resident macrophages are present in the aorta that could contribute to the macrophage population in atherosclerosis." (PMID 28771609, 2017). "Thus, we conclude that Batf3-dependent APCs have no major function in atherosclerosis." (PMID 28771609, 2017).
asthma (4 papers, 2018 to 2023). "Taken together, these data suggest that Batf KO Th9 cells can induce airway inflammation upon overexpression of Batf3 in an animal model of asthma and that BATF3 compensates for the loss of BATF." (PMID 31776325, 2019). "Our results demonstrated that in a chronic asthma model, eosinophil infiltration was impaired in cDC1-deficient Batf3−/− mice in response to inhaled OVA or papain challenge." (PMID 30250029, 2018). "Also, in the lungs of animals treated with allergen in order to induce either experimental asthma or tolerance, we found an additional cDC population (Cluster 6) which expressed Irf8, Batf3 as well as low levels of Irf4, Sirpa and Itgam." (PMID 37251386, 2023). "We have shown previously that BATF3-dependent DCs are required for immune tolerance to H. pylori and for the immunomodulatory effects of H. pylori in models of allergen-induced asthma, which in turn are driven by H. pylori-induced, highly suppressive regulatory T-cells (Tregs)." (PMID 31188899, 2019).
colon cancer (4 papers, 2019 to 2023). "A recent study demonstrated that BATF3 is expressed by intestinal epithelial cells in a model of colitis-associated colon cancer and in human cancer cell lines." (PMID 35812447, 2022). "To investigate the role of BATF3-dependent DCs in a model of T-cell driven anti-tumor immunity, we took advantage of the highly immunogenic MC38 colon cancer xenograft model, which is known to be strictly controlled by both CD4+ and CD8+ T-cells." (PMID 31188899, 2019).
colorectal cancer (4 papers, 2018 to 2022). A primary or metastatic malignant neoplasm that affects the colon or rectum. "For example, miR-760 boosts TRAIL sensitivity in non-small cell lung cancer through reducing the protein FOXA1; miR-760 suppresses human colorectal cancer growth by targeting BATF3/AP-1/cyclinD1 signaling." (PMID 31693728, 2019). "Moreover, upregulation of miR-760 suppresses proliferation of colorectal cancer cells by targeting BATF3 3′-UTR." (PMID 29661228, 2018).
cryptococcal infection (4 papers, 2015 to 2024). "Here, we demonstrate that Batf3 cDC1s are important drivers of protective Th1 CD4 T-cell responses required for clearance of cryptococcal infection." (PMID 38349130, 2024). "Using Batf3-/- mice, which lack the cDC1 population, our results support that Batf3-dependent cDC1s are pivotal for the development of the effective immune response against cryptococcal infection, particularly within the lung and brain." (PMID 38349130, 2024). "In conclusion, Batf3-dependent cDC1 can function as a linchpin in mounting Th1 response, ensuring effective fungal control during cryptococcal infection." (PMID 38349130, 2024). "The authors first used single-cell RNA sequencing to identify that Batf3-dependent cDC1 exhibited a unique mRNA signature during murine cryptococcosis, strongly upregulating transcripts related to T cell recruitment and Th1 polarization, such as Il12b, Stat4, and Ccl22." (PMID 39254303, 2024). "Deficiency in Batf3 cDC1 led to diminished CD4 accumulation and decreased IFNγ production across multiple organs, supporting that cDC1s are a major driver of potent Th1 responses during cryptococcal infection." (PMID 38349130, 2024). "Lysozyme M (LysM)-cre MHCII fl/fl (macrophages and granulocytes), BATF3−/− (CD103+ conventional dendritic cells), and CCR2−/− (monocytes and monocyte-derived dendritic cells) mice generated robust antigen-specific Th2 responses during cryptococcal infection." (PMID 25764512, 2015). "However, despite their critical role, the depletion of Batf3-dependent cDC1 cells did not significantly alter overall mouse survival or disease progression, highlighting the complex immune regulation required to survive cryptococcal infection and the need for further research in medical mycology." (PMID 39254303, 2024).
fibrosarcoma (4 papers, 2017 to 2023). A malignant mesenchymal fibroblastic neoplasm affecting the soft tissue and bone. "A similar population, termed mDC1, has recently been identified in murine fibrosarcoma and was significantly reduced in Batf3 knock-out mice, corroborating our findings that CD81+migcDC1s originate from cDC1s." (PMID 37622122, 2023).
influenza (4 papers, 2014 to 2023). An acute viral infection of the respiratory tract, occurring in isolated cases, in epidemics, or in pandemics; it is caused by serologically different strains of viruses (influenzaviruses) designated A, B, and C, has a 3-day incubation period, and usually lasts for 3 to 10 days. "Hence, we transferred psDCs or PBS to Batf3-/- mice, which lack cross-presenting cDC1s and display impaired influenza-specific CD8+ T cell responses." (PMID 37880206, 2023). "Furthermore, BATF3-/- mice that do not develop resident CD11b-CD8α+ DCs or migratory CD11b-CD103+ DCs have defective virus-specific T cell responses after WNV infection or influenza infections." (PMID 29408905, 2018).
viral infection (4 papers, 2017 to 2023). "Upon challenge with respiratory influenza virus, Batf3-/- mice failed to induce protective immunity, suggesting a protective role for cDC1 in viral infections." (PMID 38150441, 2023). "The transcription factor BATF3 is important for the development of cDC1s, as mice lacking Batf3 expression are deficient in CD8α+ DCs and tumor-resident CD103+ DCs, making them more susceptible to CD8+ T cell-controlled viral infections and tumor growth." (PMID 33268774, 2020).
colitis (3 papers, 2016 to 2022). Inflammation of the colon. "On HFD, Batf3-/- mice had a higher susceptibly to cecal inflammation during acute DSS colitis compared to WT mice." (PMID 35812447, 2022). "High-fat diet further enhanced the metabolic phenotype and susceptibility to dextran sulfate sodium colitis in Batf3-/- mice." (PMID 35812447, 2022). "To elucidate the impact that metabolic syndrome and barrier dysfunction in Batf3-/- mice might have on susceptibility to DSS colitis, we administered an HFD to WT and Batf3-/- mice from 8 to 16 weeks of age followed by 7 days of DSS drinking water." (PMID 35812447, 2022). "Furthermore, it cannot be formally excluded that CD103+CD11b− DCs are compensatory generated during the course of DSS-induced colitis in BATF3-deficient mice." (PMID 27005831, 2016). "However, we hypothesized that in the context of obesity, BATF3-deficiency may increase susceptibly to acute DSS colitis." (PMID 35812447, 2022). "To address this potential confounding factor, we induced colitis in Batf3−/− mice with an increased dose of DSS (3.5%), but again observed that peptide-mediated protection was lost in these mice." (PMID 34911745, 2021). "Previous studies using Batf3-/- mice did not observe any spontaneous development of intestinal inflammation or increased susceptibly to DSS colitis which is consistent with our findings in 8- and 16-week-old Batf3-/- mice." (PMID 35812447, 2022). "Importantly, however, note that the severity of colitis observed in Batf3−/− mice was apparently lower in comparison with that in the WT mice." (PMID 34911745, 2021). "Importantly, we found that the protection induced by the Qa-1 agonistic peptide against acute colitis (with 2.5% DSS) was lost in Batf3−/− mice in comparison with WT mice." (PMID 34911745, 2021). "TNFα is not significantly different between WT and Batf3-/- mice under HFD with acute DSS colitis." (PMID 35812447, 2022). "Acute DSS colitis in mice that were fed a HFD did not lead to significant differences in body weight, but resulted in more proximal inflammation in Batf3-/- compared to WT mice with rectal sparing, a phenotype that is reminiscent of human Crohn’s disease." (PMID 35812447, 2022).
diabetes (3 papers, 2015 to 2025). "In NOD mice, diabetes hardly progresses if cDC1 is ablated by Batf3-deficiency." (PMID 41027725, 2025). "Interestingly, a recent study observed that Batf3 deficient NOD mice did not develop diabetes." (PMID 26300591, 2015). "Deletion of the Xcr1+ NLT DC in the NOD.Batf3−/− mice resulted in absence of presentation of MHC-I epitopes in the pLN and no incidence of diabetes." (PMID 26300591, 2015).
metabolic syndrome (3 papers, 2022 to 2024). A cluster of metabolic risk factors for CARDIOVASCULAR DISEASES and TYPE 2 DIABETES MELLITUS. "Mice with a knockout of Basic leucine zipper transcription factor, ATF-like 3 (BATF3) have disrupted gut barrier function, inefficient response to oral immunization, and increased susceptibility to metabolic syndrome." (PMID 39457699, 2024). "Here, we demonstrate that BATF3-deficiency leads to the development of metabolic syndrome as characterized by insulin resistance, blood glucose and serum insulin levels, increased body weight and white adipocyte size, and development of hepatosteatosis." (PMID 35812447, 2022). "Our data suggest that BATF3-deficiency leads to altered IgA-coating of bacteria, and intestinal dysbiosis that could contribute to the development of metabolic syndrome." (PMID 35812447, 2022). "Our data suggest that deficiency of the transcription factor BATF3 results in phenotypical changes of IgA-coating of bacteria, microbial dysbiosis, and impairs intestinal epithelial barrier function, leading to low-grade inflammation that contributes to the development of metabolic syndrome." (PMID 35812447, 2022). "Moreover, Batf3-deficient mice presented increased dyslipidemia and liver alterations." (PMID 34983945, 2022). "In summary, these data show an important role of the intestinal microbiota in the development of metabolic syndrome and pro-inflammatory LP phenotype observed in Batf3-/- mice." (PMID 35812447, 2022). "Although our study focused on the consequences of deficiency in BATF3-dependent cDC1s in the lamina propria, a role of BATF3-dependent DCs in other organs that contribute to metabolic syndrome can’t be excluded." (PMID 35812447, 2022). "To evaluate the role of BATF3 in the development of metabolic syndrome, we first administered standard chow and measured the percentage of weight gain of WT and Batf3-/- mice from the age of 8 to 16 weeks." (PMID 35812447, 2022). "To further investigate the role of intestinal microbiota in the development of metabolic syndrome in Batf3-/- mice, we performed 16S rRNA gene sequencing on 8-week-old WT and Batf3-/- mice before the onset of metabolic syndrome." (PMID 35812447, 2022). "In this study, we investigated the role of BATF3 in maintaining intestinal barrier and development of metabolic syndrome." (PMID 35812447, 2022). "Using Batf3-/- mice with a specific depletion of lamina propria CD103+ cDC1 suggests a role for this subset in the development of metabolic syndrome and the pro-inflammatory phenotype." (PMID 35812447, 2022). "Our data suggest that BATF3 plays a protective role in the development of intestinal inflammation under conditions of metabolic syndrome." (PMID 35812447, 2022). "We show that Batf3-/- mice developed metabolic syndrome and have altered localization of tight junction proteins in intestinal epithelial cells leading to increased intestinal permeability." (PMID 35812447, 2022). "To investigate the role of intestinal bacteria in the development of metabolic syndrome in Batf3-/-, we treated WT and Batf3-/- mice with broad-spectrum antibiotics (Abx) from the time of weaning until 16 weeks of age." (PMID 35812447, 2022). "Antibiotic treatment of Batf3-/- mice prevented metabolic syndrome and impaired intestinal barrier function." (PMID 35812447, 2022). "In summary, we demonstrate that BATF3 plays a protective role in the development of metabolic syndrome by mechanisms involving the intestinal microbiome, regulation of intestinal epithelial cell homeostasis, and prevention of low-grade intestinal inflammation." (PMID 35812447, 2022). "In addition to the development of obesity in Batf3-/- mice, we also observed symptoms of metabolic syndrome in Batf3-/- mice." (PMID 35812447, 2022). "Thus, BATF3 plays an important role in preventing the development of metabolic syndrome through a microbiome-dependent mechanism." (PMID 35812447, 2022).
metabolic syndrome (continued). "Our findings demonstrate that BATF3 is required to maintain a healthy intestinal barrier and prevent the development of intestinal dysbiosis and chronic low-grade inflammation that contributes to the development of metabolic syndrome." (PMID 35812447, 2022). "This hypothesis is supported by our data, demonstrating that antibiotic treatment of Batf3-/- mice prevented the development of metabolic syndrome and low-grade inflammation." (PMID 35812447, 2022). "Irf8-/- mice did not develop metabolic syndrome and we did not observe any deficiency in enteroid formation, most likely because the defects in enteroid formations in Batf3-/- mice are driven by metabolic changes including hyperglycemia." (PMID 35812447, 2022). "Taken together, these studies and our findings suggest that changes in the abundance of specific bacteria in Batf3-/- mice may trigger or contribute to the development of metabolic syndrome." (PMID 35812447, 2022). "Thus, BATF3 protects against metabolic syndrome and preserves intestinal epithelial barrier by maintaining beneficial microbiota." (PMID 35812447, 2022). "Although the treatment with 2-DG for 10 days may not be sufficient to reverse the metabolic syndrome in these mice, it demonstrates the central role of glucose metabolism in intestinal epithelial cells to the loss of barrier integrity and pro-inflammatory phenotype in the gut of Batf3-/- mice." (PMID 35812447, 2022).
steatosis (3 papers, 2020 to 2026). Increased lipid within the cytoplasm of cells. "While study has also found that the adoptive transfer of CD103+ DCs to Batf3 deficient mice with steatohepatitis significantly alleviated the steatosis with improvement of inflammation and cell injury." (PMID 32283569, 2020). "Batf3 KO animals demonstrated a switch towards MASH from steatosis under high sucrose diet (HSD) including an increased presence of inflammatory infiltrates, steatosis, and elevated hepatocellular damage compared to WT animals." (PMID 38650949, 2024).
classical Hodgkin lymphoma (2 papers, 2018 to 2021). "It is well recognized that the AP-1 transcription factor BATF3 is constitutively expressed in Hodgkin/Reed-Sternberg (HRS) cells, but its potential as a diagnostic marker for classical Hodgkin lymphoma (cHL) has not yet been addressed." (PMID 34202976, 2021).
fatty liver disease (2 papers, 2022 to 2026). A reversible condition wherein large vacuoles of triglyceride fat accumulate in liver cells via the process of steatosis. "Although recent studies suggest that BATF3 is involved in metabolic disorders, the mechanism by which BATF3 deficiency contributes to the development of metabolic dysfunction-associated fatty liver disease (MASLD) remains unclear." (PMID 42157937, 2026). "Collectively, our findings provide mechanistic insights into how BATF3 regulates hepatic and adipose homeostasis, contributing to fibrosis development, and highlight the BATF3-ANGPTL8 axis as a potential therapeutic target in fatty liver disease." (PMID 42157937, 2026).
Insulin resistance (2 papers, 2022). Increased resistance towards insulin, that is, diminished effectiveness of insulin in reducing blood glucose levels. "We demonstrate that Batf3-/- mice present with impaired intestinal barrier function at 16 weeks of age, which is associated with the development of insulin resistance and hepatosteatosis." (PMID 35812447, 2022). "Moreover, we found that fasting glucose levels, glucose disposal during a glucose tolerance test, and insulin resistance were ameliorated in Batf3KO mice reconstituted with WT BM compared to those adoptively transferred with Batf3-deficient BM." (PMID 34983945, 2022). "However, Batf3-deficient mice showed higher insulin resistance than their WT counterparts." (PMID 34983945, 2022). "Batf3-/- mice had significantly higher blood glucose concentration after i.p. injection of insulin compared to WT mice at 16 weeks, indicating insulin resistance in these mice." (PMID 35812447, 2022). "However, at 16 weeks of age Batf3-/- mice had a HOMA-IR score of 4.6, while WT mice had a HOMA-IR score of 0.8, indicating insulin resistance in Batf3-/- mice." (PMID 35812447, 2022).